CD34 (CD34 molecule)
Diseases named in the same sentence as CD34 in open-access papers (continued):
Sharing a sentence is not in itself a finding about the gene and the disease.
neurothekeoma (1 paper, 2020). A benign neoplasm arising from nerve sheaths. "TCs/CD34+SCs are described as an associated, reactive component in nerve sheath myxoma, considered either a myxoid/hypocellular variant of neurothekeoma or a distinctive S-100-positive myxoid peripheral nerve sheath tumour." (PMID 32560571, 2020).
ovarian angiosarcoma (1 paper, 2025). A malignant vascular neoplasm arising from the ovary. "By immunohistochemistry, the most common markers expressed in ovarian angiosarcoma, primary and secondary, include CD31 (100%), CD34 (98%), vimentin (100%), and factor VIII-related gene (85.7%)." (PMID 41322900, 2025).
Paget disease (1 paper, 2020). A malignant neoplasm composed of large cells with large nuclei, prominent nucleoli, and abundant pale cytoplasm (Paget cells). "As a parameter related to blood flow in the nipple, the total CD34-positive blood vessel lumen area relative to the entire nipple area was measured in each Paget disease and control case using an automated image analysis system." (PMID 32527320, 2020). "The ratio of the CD34-positive blood vessel lumen area to nipple area was also significantly higher in the Paget disease than control cases (p = 0.003)." (PMID 32527320, 2020). "In this study, a dramatic increase in the number of CD34-positive blood vessels, with a minor proportion of podoplanin (D2–40)-positive lymphatic vessels, was observed in the Paget disease group." (PMID 32527320, 2020). "We also examined the total area of CD34-positive vessel structures to estimate the blood flow volume in Paget disease and normal nipple tissues." (PMID 32527320, 2020). "Indeed, our results demonstrated a significant increase in the average LVD in Paget disease and its positive correlation with bFGF expression; however, podoplanin (D2–40)-positive lymphatic vessels comprised a minor proportion of the vessels compared with the CD34-positive blood vessels." (PMID 32527320, 2020).
papillary thyroid carcinoma (1 paper, 2021). "In the pathological evaluation, CD34-, CD117-, MPO-, and HLA-DR-positive blastic cells which infiltrated into follicular variant papillary thyroid carcinoma were detected." (PMID 34325712, 2021).
papilloma (1 paper, 2014). A benign epithelial neoplasm that projects above the surrounding epithelial surface and consists of villous or arborescent outgrowths of fibrovascular stroma. "However, another study showed that well-organized, differentiated papillomas containing CD34, β4-integrin, and K15-expressing cells (CSC markers) gave rise to layers of differentiated tissues." (PMID 25013928, 2014). "In contrast to Meis1 expression in normal epidermis, we found that Meis1-EGFP was not co-expressed with β4 integrin, CD34, or K15 in the tumor basal layers, where epidermal cancer stem cells are thought to reside in papillomas." (PMID 25013928, 2014).
parathyroid adenomas (1 paper, 2023). "(d) TCs/CD34+ SCs associate with collagen I, which is increased and surrounded by these cells in the adventitia of vessels in parathyroid glands compressed by parathyroid adenomas." (PMID 37569493, 2023). "Likewise, the formation of large cell masses in parathyroid adenomas, with compact accumulations of parenchymal cell nests containing small vessels devoid of perivascular stromal cells, may explain the absence of TCs/CD34+ SCs in large regions of them." (PMID 37569493, 2023).
periapical granuloma (1 paper, 2024). Chronic nonsuppurative inflammation of periapical tissue resulting from irritation following pulp disease or endodontic treatment. "This study is the first to evaluate the presence of the CD34+ and Ki-67+ proliferating vessels in periapical granulomas." (PMID 39518412, 2024). "Another study that focused on the presence of CD34 in periapical granulomas reported an increased expression of this molecule, determining the existence of an endothelial hyperplasia due to the increased angiogenesis." (PMID 39518412, 2024). "This study will determine the immunoexpression of CD34 and Ki-67 in periapical granulomas and assess their impact on the growth and development of this tissue, as well as consider their roles in the proliferative process and aggressiveness of evolution." (PMID 39518412, 2024). "By targeting CD34 in periapical granulomas, we aimed to quantify angiogenesis in the pathological tissue." (PMID 39518412, 2024). "The present study aims to identify and evaluate the immunoexpression of CD34 and Ki-67 in periapical granulomas, as well as determine their influence on the development and progress of this type of tissue, considering their influence on the proliferative process and aggressiveness of evolution." (PMID 39518412, 2024). "Thus, based on these results, our study is the only one to evaluate both Ki-67 and CD34 expression in periapical granulomas." (PMID 39518412, 2024).
peripartum cardiomyopathy (1 paper, 2021). Peripartum cardiomyopathy (PPCM) is an idiopathic, potentially fatal form of dilated cardiomyopathy that develops during the final month of pregnancy or within five months after delivery. "In our recently published study on women who recovered from peripartum cardiomyopathy, we found significantly higher sFlt1 (VEGF‐R) levels with a clear trend toward lower circulating CD34+/KDR+ levels compared to healthy controls, suggesting an endothelial imbalance." (PMID 33955558, 2021).
persistent atrial fibrillation (1 paper, 2018). "Accordingly, in a study with patients with persistent atrial fibrillation, increased ANP levels in the peripheral blood were shown to correlate with increase in the expression of SDF1α and CD34+ hematopoietic progenitor cells." (PMID 29348441, 2018).
phenylketonuria (1 paper, 2024). Phenylketonuria (PKU) is the most common inborn error of amino acid metabolism and is characterized by mild to severe mental disability in untreated patients. "CD34+ hematopoietic stem cells, Rubius used bioengineering technology on CD34+ hematopoietic stem cells from healthy O-type donors for cell therapy products, such as RTX-134 for PKU (phenylketonuria), RTX-240 for AML, and RTX-321 (RTX-aAPC) for HPV 16+ cancer." (PMID 38164142, 2024).
placental hemangioma (1 paper, 2014). A hemangioma arising from the fetal blood vessels in the placental villi. "Positivity for CD31 and CD34 endothelial cells markers was detected as well as focal positivity for the cytokeratin 18 marker, leading to the diagnosis of placental hemangioma (chorioangioma)." (PMID 25295202, 2014).
pleural mesothelioma (1 paper, 2014). A neoplasm that arises from the mesothelial cells of the pleura. "In addition, malignant pleural mesothelioma cells are negative for vascular endothelial marker (CD31 and CD34) expression." (PMID 25364420, 2014).
pleural tumors (1 paper, 2022). "SFTPs are primary tumors arising from CD34-positive dendritic mesenchymal cells and account for < 5% of all pleural tumors." (PMID 35641960, 2022).
pneumococcal infection (1 paper, 2014). Infections with bacteria of the species streptococcus pneumoniae. "Pneumococcal infection did not induce changes in these cell populations since the levels of bone marrow cells with blastoid morphology, their expression of Gr-1 and CD34+ cells in both WNC and MNC mice were equal to basal levels." (PMID 24691464, 2014). "As described for WNC and MNC mice, the pneumococcal infection did not induce changes in these cell populations since the levels of bone marrow cells with blastoid morphology, their expression of Gr-1 and CD34+ cells in BDC, BCD+LrO and BCD+LrN mice were equal to basal levels." (PMID 24691464, 2014).
polyposis (1 paper, 2019). "By transferring CD34 CD43 deficient bone marrow to lethally irradiated APCΔ468 mice we were able to efficiently block MCp homing of bone marrow derived MCp to the gut, and attenuated polyposis." (PMID 31849960, 2019).
prion disease (1 paper, 2014). A transmissible disease that is caused by a protein that is able to induce abnormal folding of normal cellular proteins, leading to characteristic spongiform brain changes, which are associated with neuronal loss without an inflammatory response. "First, we analyzed the expression of CD34+ during prion disease, an antigen reported as characteristic of proliferating microglial cells." (PMID 24648328, 2014). "CD34+ cells show a trend to be more numerous in prion disease mice when compared with the NBH group, more evident in the thalamus at late-stage disease." (PMID 24648328, 2014). "However, further experiments would be necessary to support the existence of a highly proliferative CD34+ microglial subpopulation in prion disease." (PMID 24648328, 2014). "Our results show some expansion of the CD34+ cell population, independent of the recruitment of circulating progenitors to the microglial pool, supporting previous studies highlighting the important role of proliferation of resident microglial cells in prion disease." (PMID 24648328, 2014).
prostate (1 paper, 2010). "We wanted to look at the expression of PSMA in blood vascular, we stained adjacent sections with anti-CD34 and anti-PSMA antibodies of our samples and we found that endothelium of both benign and malignant prostate tissues were deprived from PSMA expression." (PMID 21189143, 2010).
protein (1 paper, 2017). "There is regeneration of the liver tissue due to protein energy malnutrition, decrease of Hsp70 expression, increase of VEGF-1 expression, and high expression of CD34 and CD45." (PMID 28717326, 2017).
Psoriasiform dermatitis (1 paper, 2019). A skin abnormality characterized by redness and irritation, with thick, red skin that displays flaky, silver-white patches (scales).
pulmonary sarcoidosis (1 paper, 2020). Sarcoidosis affecting the lung parenchyma. "Previous studies have shown that in untreated patients with newly diagnosed pulmonary sarcoidosis, the number of CD34+ peripheral blood cells is significantly higher compared to the control group." (PMID 33218322, 2020).
radicular cysts (1 paper, 2020). "The present study aimed to evaluate the immunohistochemical expression of CD34 and α-SMA in radicular cysts (RC) and residual radicular cysts (RRC), with the purpose of contributing to a better understanding of the expansion and progression of these periapical lesions." (PMID 32388520, 2020).
relapsing-remitting multiple sclerosis (1 paper, 2018). The most common clinical variant of multiple sclerosis, characterized by recurrent acute exacerbations of neurologic dysfunction followed by partial or complete recovery. "In a phase II clinical trial, high-dose immunosuppressive therapy combined with autologous CD34+ hematopoietic stem cell transplant in treatment-resistant, relapsing-remitting multiple sclerosis (RRMS) resulted in 69.2% of participants achieving long-term remission through 60 months follow-up." (PMID 29456529, 2018).
renal failure (1 paper, 2015). "Because identical ischaemic injury in neutropenic mice reduced renal insufficiency and significantly reduced mortality, it was deduced that adverse effects of pharmacological CD34-positive cells mobilization were primarily mediated by the concomitant induction of marked granulocytosis." (PMID 25389045, 2015).
Rett syndrome (1 paper, 2025). A severe neurodevelopmental disorder affecting the central nervous system. "Although early in development, our current proof-of-concept experiments, we evaluated the efficacy ofMECP2 expressing lentiviral vector transduced human CD34+ HSPC transplanted in an immunodeficient mouse model of Rett syndrome." (PMID 40893333, 2025).
rosacea (1 paper, 2021). A chronic erythematous skin disorder that affects the face. "CD34+SCs/TCs are absent in perifolliculitis and the perifollicular and perivascular inflammatory infiltrate present in rosacea." (PMID 34298962, 2021). "In rosacea, the absence of CD34+SCs/TCs is irrespective of the inflammatory cells in the different stages of the lesion (lymphocytic, mixed or granulomatous)." (PMID 34298962, 2021).
rotator cuff tear (1 paper, 2016). "CD34 (a blood vessel marker) immunoreactions: CD34 was strongly expressed in the capsular tissue in 6 FS patients (75 %) but in only 1 rotator cuff tear patient (10 %), supporting increased vascularity in the FS samples." (PMID 27527912, 2016).
sarcoidosis (1 paper, 2020). Sarcoidosis is a multisystemic disorder of unknown cause characterized by the formation of immune granulomas in involved organs. "The aim of the present study was to evaluate the immunophenotype of the CD34+ cell population in peripheral blood in patients with newly diagnosed sarcoidosis with reference to the control group." (PMID 33218322, 2020). "Our previous studies showed a significantly higher percentage of CD34 + progenitor cells in the PB in patients with newly diagnosed sarcoidosis compared to the control group and showed a positive correlation with CD4/CD8 ratios." (PMID 33218322, 2020). "The heterogeneous CD34+ cells population was divided and characterized in PB patients with sarcoidosis." (PMID 33218322, 2020). "This study was to evaluate the immunophenotype of the CD34+ cell population in PB in patients with newly diagnosed sarcoidosis with reference to the control group and exact characteristics low-differentiated CD34+ cells including DLCO values in sarcoidosis." (PMID 33218322, 2020). "Fibrocytes and EPC were analyzed among low-differentiated CD34+ cells in these two groups with sarcoidosis." (PMID 33218322, 2020). "This study demonstrated for the first time the characterization of immunophenotype of peripheral CD34+ cells with the degree of their differentiation in patients with sarcoidosis." (PMID 33218322, 2020). "Our previous studies showed a significantly higher percentage of CD34 + cells in the peripheral blood in patients with sarcoidosis (SA) compared to the control group." (PMID 33218322, 2020). "CD34+ progenitor cells may be important in the pathogenesis of sarcoidosis." (PMID 33218322, 2020). "Among all low-differentiated cells CD34+, the median proportion of fibrocytes was 1.309% (0.288–2.048) and EPC accounted for 0.519% (0.231–1.317) in all patients (group I and II) with sarcoidosis." (PMID 33218322, 2020). "No literature characterizing the population of CD34+ cells in patients with sarcoidosis has been found." (PMID 33218322, 2020).
SARS-CoV infection (1 paper, 2009). "Our observation reveals the BASCs (Sca-1+ CD34+ CD45- Pecam-), a subset of Oct-4+ ACE2+ epithelial colony cells at the broncho-alveolar duct junction, to be the prime target cells of SARS-CoV infection." (PMID 19915717, 2009).
sebaceous tumours (1 paper, 2015). "In addition, expression of bulge SC marker molecules, including NFATc1, K15 and CD34 were decreased in sebaceous tumours." (PMID 25608467, 2015). "Astonishingly, expression of mutant Lef1 was higher in CD34+/Itga6high SCs from K14ΔNLef1 mice indicating that lower expression levels of mutant Lef1 driven by the K15 promoter allow for initiation of sebaceous tumours, which differ with respect to morphology, differentiation and aggressive growth." (PMID 25608467, 2015). "Taken together, these experiments indicate that although bulge SCs are a cell-of-origin for sebaceous tumours in their normal SC environment, CD34+ tumour cells do not propel tumour cell propagation following transplantation." (PMID 25608467, 2015).
seborrheic keratosis (1 paper, 2021). A common benign skin neoplasm usually affecting older individuals. "In seborrheic keratosis, CD34+ stromal cells are located at the bottom of the lesion, but are not observed in the papillary areas with papillomatosis." (PMID 34298962, 2021).
Shwachman-Diamond syndrome (1 paper, 2014). "We also observe an increase of autophagy in cells derived from DBA patients, in CD34+ erythrocyte progenitor cells with RPS19 knock down, in the red blood cells of zebrafish embryos with RP-deficiency, and in cells from patients with Shwachman-Diamond syndrome (SDS)." (PMID 24875531, 2014).
sideroblastic anaemia (1 paper, 2015). "In contrast, mice injected with CD34+ cells from a congenital sideroblastic anaemia patient showed myeloid as well as lymphoid cell engraftment." (PMID 26643973, 2015).
Sleep apnea (1 paper, 2019). An intermittent cessation of airflow at the mouth and nose during sleep is known as sleep apnea. "In our study, we demonstrated that CPAP has potential benefits in mostly moderate to severe OSA patients with 12 weeks of intervention but the improvement in the number and functionality of EPCs (CD34+) as well as in AS is limited according to the severity of the sleep apnea degree." (PMID 31113468, 2019).
small cell carcinoma (1 paper, 2021). A neuroendocrine carcinoma composed of small malignant cells which are often said to resemble "oat cells" under the microscope. "However, the small cell carcinoma component was negative for CD34 and c-kit (CD117)." (PMID 34596138, 2021).
small cell carcinoma of the ovary (1 paper, 2012). "A single case of small cell carcinoma of the ovary expressing CD34 has been described in the literature." (PMID 23346438, 2012).
smallpox (1 paper, 2021). A condition that is caused by infection with Variola, and that is characterized by small, raised bumps. "In conclusion, our results indicate that hu-CD34+ and hu-BLT mice will be valuable as models of human smallpox for continued development of pre- and post-exposure treatments." (PMID 34547055, 2021).
spina bifida (1 paper, 2023). A congenital neural tube defect in which vertebrae are not fully formed. "It was illustrated that administration of CD34+ cells in combination with MSCs enhanced putative blood vessel formation and peripheral nerve growth in spina bifida patients, which, in turn, promoted the improvement of bladder function." (PMID 37118832, 2023).
spinal cord ischemia (1 paper, 2016). Reduced blood flow to the spinal cord which is supplied by the anterior spinal artery and the paired posterior spinal arteries. "Hence, GDF15 may be secreted from CD34-positive cells that have been mobilized in peripheral blood following IPC, explaining the protective effects against spinal cord ischemia." (PMID 27905554, 2016).